TNK1 (tyrosine kinase non receptor 1)
Description:
Involved in negative regulation of cell growth. Has tumor suppressor properties. Plays a negative regulatory role in the Ras-MAPK pathway. May function in signaling pathways utilized broadly during fetal development and more selectively in adult tissues and in cells of the lymphohematopoietic system. Could specifically be involved in phospholipid signal transduction.
Synonyms: KOS1
Tractability: Small molecule: a high-quality ligand is known; it belongs to a druggable protein family. Antibody: UniProt places it where antibodies can reach, with high confidence; its Gene Ontology location is reachable by antibodies, with medium confidence. PROTAC: it is named in the literature on targeted protein degradation; ubiquitination databases record sites on it; a small molecule that binds it is known.
Target class: Tyrosine protein kinase Ack family; TK protein kinase group; Enzyme; Protein Kinase; Kinase
Gene: Protein-coding gene on chromosome 17 (7,380,534 to 7,389,774, forward strand). Ensembl gene ENSG00000174292.
Subcellular location: Cytoplasm; Membrane
Subcellular location (Human Protein Atlas): Cell Junctions
Gene Ontology:
Molecular function: ATP binding; protein binding; protein tyrosine kinase activity; non-membrane spanning protein tyrosine kinase activity; protein kinase activity
Biological process: protein autophosphorylation; protein phosphorylation
Cellular component: cytoplasm; membrane; plasma membrane
Genetic constraint (gnomAD): Loss-of-function variants: 53 observed, 58.49 expected, observed/expected ratio (o/e) 0.91, 90% interval 0.73 to 1.14. The upper end of that interval is the gene's LOEUF score, 1.14, which puts it in group 4 of 6, group 1 being the genes least tolerant of losing a copy. Missense variants: 831 observed, 811.98 expected, observed/expected ratio (o/e) 1.02, 90% interval 0.97 to 1.08. Synonymous variants: 352 observed, 325.27 expected, observed/expected ratio (o/e) 1.08, 90% interval 0.99 to 1.18.
Homologues: Orthologues: chimpanzee TNK1 (99% identical), macaque TNK1 (97% identical), rabbit TNK1 (86% identical), dog TNK1 (86% identical), pig TNK1 (86% identical), mouse Tnk1 (84% identical), rat Tnk1 (84% identical), guinea pig TNK1 (83% identical). Paralogues in human: TNK2 (42% identical), ABL1 (22% identical), PTK2 (22% identical), ABL2 (21% identical), PTK2B (21% identical), FRK (18% identical), SRMS (18% identical), LCK (18% identical), SRC (18% identical), FGR (17% identical), FYN (17% identical), JAK3 (17% identical), and 20 more.
Diseases named in the same sentence as TNK1 in open-access papers:
TNK1 is named in the same sentence as 18 diseases in open-access papers, as found by Europe PMC text mining. Sharing a sentence is not in itself a finding about the gene and the disease. The quoted sentences say what the papers report.
Hodgkins lymphoma (4 papers, 2012 to 2022). A heterogeneous group of malignant lymphoid neoplasms of B-cell origin characterized histologically by the presence of Hodgkin and Reed-Sternberg (HRS) cells in the vast majority of cases. "The Hodgkin lymphoma (HL) cell line L540 carries a paracentric chromosomal inversion that truncates TNK1 at D472, generating an active and highly expressed form of TNK117." (PMID 34504101, 2021). "One example is the Hodgkin lymphoma cell line L540, in which a paracentric inversion generated a truncated TNK1 that lacks the 14-3-3 binding site." (PMID 34504101, 2021). "In contrast to this function, TNK1 was identified as a potentially oncogenic tyrosine kinase in a mutagenesis screen and activated TNK1 was found in Hodgkin's lymphoma." (PMID 22615583, 2012). "Furthermore, in the Hodgkin lymphoma cell line L540, a C-terminally truncated and constitutively active form of TNK1 is essential for cell growth and survival." (PMID 34504101, 2021). "TNK1 sorted out as an important kinase with oncogenic potential implicated in hematological carcinogenesis such as in AML and Hodgkin’s Lymphoma which suggests that targeted intervention of TNK1 may open new platform for therapy." (PMID 29455667, 2018). "We also studied a fusion protein, originally discovered in a Hodgkin’s Lymphoma cell line, that contains an unrelated sequence from the C17ORF61 gene fused to the C-terminus of Tnk1." (PMID 36334623, 2022).
Alzheimer disease (2 papers, 2020 to 2022). A progressive, neurodegenerative disease characterized by loss of function and death of nerve cells in several areas of the brain leading to loss of cognitive function such as memory and language. "A possible mechanism involves the ability of Tnk1 to induce TNFα-dependent apoptosis by preventing activation of NF-κB, as TNFα is known to be important in driving the progression of Alzheimer’s disease." (PMID 36334623, 2022). "Besides atherosclerosis, TNK1 also participates in several other diseases, such as atypical dementia, Alzheimer's Disease, and colorectal cancer." (PMID 32694928, 2020).
lymphoma (2 papers, 2021 to 2022). A malignant (clonal) proliferation of B- lymphocytes or T- lymphocytes which involves the lymph nodes, bone marrow and/or extranodal sites. "A unique form of Tnk1 was discovered in the Hodgkin’s Lymphoma cell line L540: the 5′ portion of the Tnk1 gene (encoding the kinase domain) was fused to sequences from the C17ORF61 (chromosome 17 open reading frame 61) gene." (PMID 36334623, 2022). "A Tnk1 variant with a truncated C-terminus fused to a 39-residue segment from C17ORF61 (Tnk1Fusion) showed increased activity (relative to WT Tnk1) in a Hodgkin’s Lymphoma cell line." (PMID 36334623, 2022).
atherosclerosis (1 paper, 2020). A disease characterized by the build-up of fatty material and calcium deposition in the arterial wall resulting in partial or complete occlusion of the arterial lumen. "To explore the functions of TNK1 in atherosclerosis, we detected the expression of TNK1 in different cell lines, using GAPDH as reference." (PMID 32694928, 2020). "The present study was to investigate the anti-inflammation effects and mechanisms of TNK1 in atherosclerosis and the involvement of Tyk2/STAT1 signal in the functions of TNK1." (PMID 32694928, 2020). "We also found that shTNK1 inhibited the uptake of lipid in macrophages, which confirmed the roles of TNK1 in atherosclerosis." (PMID 32694928, 2020). "The present study was to investigate the anti-inflammatory functions and mechanisms of TNK1 in atherosclerosis." (PMID 32694928, 2020). "In summary, TNK1 participated in the inflammation in atherosclerosis." (PMID 32694928, 2020). "This inspired us to investigate the functions of TNK1 in the inflammation of atherosclerosis." (PMID 32694928, 2020).
bladder cancer (1 paper, 2020). "The expression of TNK1 and C16orf74 is inhibited by hypermethylation, which leads to a worse prognosis of bladder cancer." (PMID 32843852, 2020). "Besides, the methylation level of TNK1 and C16orf74 can also predict the prognosis of bladder cancer." (PMID 32843852, 2020).
Crohn disease (1 paper, 2022). A gastrointestinal disorder characterized by chronic inflammation involving all layers of the intestinal wall, noncaseating granulomas affecting the intestinal wall and regional lymph nodes, and transmural fibrosis. "On the other hand, Tnk1 induces apoptosis in intestinal epithelia, and expression of Tnk1 is increased in patients with Crohn’s disease." (PMID 36334623, 2022).
leukaemia (1 paper, 2015). "Scarce knowledge exists about TM256, but it has been shown in leukaemia cells that a TM256-fusion protein with non-receptor tyrosine kinase TNK1 (TNK:C17orf61) leads to a constitutively active TNK1 that is associated with uncontrolled growth." (PMID 26196085, 2015).
lung carcinoma (1 paper, 2022). "Overexpression of Kos1 (the murine homolog of Tnk1) in Ras (G12V)-driven lung cancer cells inhibited cell growth." (PMID 36334623, 2022).
mammary tumor (1 paper, 2023). "XAV939 (TNK1/2 inhibitor) enhanced cytotoxic effect of LY294002 (inhibitor of PI3Kα/δ/β and other proteins) in PIK3CAH1047R-expressing mouse mammary tumor cells." (PMID 37471270, 2023).
Multiple Organ Failure (1 paper, 2020). A progressive condition usually characterized by combined failure of several organs such as the lungs, liver, kidney, along with some clotting mechanisms, usually postinjury or postoperative. "Recently, we described the detrimental effects of enhanced TNK1 expression in the gut as a driver of multiple-organ failure." (PMID 32983160, 2020). "Based on recent findings of intestinal mechanisms in development of multiple-organ failure, TNK1 has been proposed as a “gateway to multiple-organ failure”." (PMID 32983160, 2020).
pancreatic cancer (1 paper, 2024). "TNK1 has been observed to promote apoptosis induced by the tumor necrosis factor alpha and its activity has been shown to stimulate growth and survival of pancreatic cancer cells." (PMID 39446839, 2024).
tumor (12 papers, 2011 to 2025). "Alterations of TNK1 included mRNA down-regulation or mutations in 22 out of 195 cases (13 %) across all tumor stages." (PMID 26388988, 2015). "To measure the ability of TNK1-driven Ba/F3 cells to grow in vivo, we stably integrated luciferase into the parental Ba/F3 cells for bioluminescent imaging of tumor burden, followed by retroviral expression of our panel of TNK1 variants and BCR-ABL." (PMID 34504101, 2021). "The TNK1 ΔUBA-AAA cells established low levels of tumor burden, but these cells were primarily confined to the tail and were remarkably benign in this model." (PMID 34504101, 2021). "Previous studies on TNK1, while limited in number, have been mixed with some suggesting a tumor-suppressive function and others a pro-survival/oncogenic function." (PMID 34504101, 2021). "In contrast to ACK1, however, Tnk1 is believed to have tumor suppressor function by interfering with Ras signaling, making it an unlikely candidate for functional redundancy with ACK1 in respect to oncogenic signaling pathways." (PMID 33730447, 2021). "In a murine model, in which mice were injected with Ba/F3 cells via the tail vein, we found that TNK1-AAA-driven cells established rapid tumor burden and induced mortality with similar kinetics to BCR-ABL." (PMID 34504101, 2021). "Finally, we identify a TNK1 inhibitor, TP-5801, which shows nanomolar potency against TNK1-transformed cells and suppresses tumor growth in vivo." (PMID 34504101, 2021). "TNK1 is a tumor suppressor that can down-regulate the activity of Ras." (PMID 32843852, 2020). "Available literature reveals that TNK1 has both tumor suppressing and oncogenic potential as it can mitigate the growth of tumor cells by dowenregulating Ras-Raf1-MAPK pathway, induce apoptosis through NF-κB inhibition, activate cellular transformation and growth of neoplastic cells." (PMID 29455667, 2018). "Mutant mice having deletions in the kinase domain of TNK1 develop spontaneous tumors at a high frequency, which is thought to originate from hyperactivation of Ras signaling and suggests that TNK1 functions as a tumor suppressor." (PMID 22615583, 2012). "Tnk1/Kos1 knockout in mice results in an increased rate of tumor development." (PMID 21637378, 2011). "Tnk1/Kos1 have been reported to have proapoptotic or tumor-suppressor functions." (PMID 21637378, 2011). "In cancer, Tnk1 may act as a tumor suppressor or as an oncogene, depending on cell context." (PMID 36334623, 2022). "Specifically, by targeting TNK1, an inhibitor of the Grb2-Sos1 GEF complex, miR-135b-5p may activate the MAPK/ERK signaling pathway and in turn promote tumor progression." (PMID 36755690, 2023). "In contrast, mice injected with WT- and TNK1 ΔUBA-expressing cells showed no detectable tumors nor physical signs of tumor burden." (PMID 34504101, 2021). "Genes related to cancer pathways were downregulated upon atezolizumab treatment, including angiogenic factors for tumor vascularization (TNK1, AREG and KDR), proto-oncogenes (RET and MET) and tumor cell survival/migration/invasion (CDH1, RARA, WNK2, WNT4A, WNT9A, TGFB2, EGF, and LAMA3)." (PMID 32616706, 2020).
cancer (3 papers, 2020 to 2024). A tumor composed of atypical neoplastic, often pleomorphic cells that invade other tissues. "As LKB1 can activate MARKs, it is possible that cancers deficient in LKB1 may have higher levels of active TNK1 (via inactivation of MARKs)." (PMID 34504101, 2021). "We propose that these observations help guide future work to evaluate TNK1 as a therapeutic target in specific cancer settings." (PMID 34504101, 2021). "The mechanisms underlying the activity of non-receptor tyrosine kinase, TNK1, in cancers are unclear." (PMID 34504101, 2021). "Here, we identify TNK1 dependencies in primary human cancers." (PMID 34504101, 2021). "Based on our data, we suspect that MARK- and 14-3-3-mediated suppression of TNK1 may be a point of deregulation in cancer to ‘turn on’ TNK1." (PMID 34504101, 2021). "However, some of the genes harboring AT/RT-unique differentiation–demethylated DMRs with EZH2 binding, such as TNK1, are found to be relevant in cancer development and have not been associated with nBAF or late neural development." (PMID 38499326, 2024).
hematological cancers (1 paper, 2021). "We began this study with the identification of TNK1 as an essential tyrosine kinase in a subset of hematological cancers." (PMID 34504101, 2021).
TNK1 also shares sentences with these, for which no sentence is quoted: colorectal cancer (2 papers); infection (1); intestinal disorder (1); kidney injury (1).